CNP (2',3'-cyclic nucleotide 3' phosphodiesterase)
Description:
Myelin-associated enzyme that catalyzes the phosphodiester hydrolysis of 2',3'-cyclic nucleotides to 2'-nucleotides. In the mitochondria, regulates the functioning of the mitochondrial permeability transition pore (mPTP), and thus is involved in the mechanisms of cell death, both apoptosis and necrosis. Acts as an antiviral factor by suppressing the assembly of SARS-CoV-2 virions. Acts as an antiviral factor by suppressing the assembly of HIV-1 virions through direct interaction with GAG.
Synonyms: CN37; CNP1; HLD20
Tractability: Small molecule: it has a binding pocket of medium quality. Antibody: the Human Protein Atlas places it where antibodies can reach. PROTAC: ubiquitination databases record sites on it; its protein half-life has been measured.
Target class: Enzyme; Hydrolase
Gene: Protein-coding gene on chromosome 17 (41,966,763 to 41,977,740, forward strand). Ensembl gene ENSG00000173786.
Subcellular location: Melanosome; Mitochondrion; Cell membrane (Isoform CNPI)
Subcellular location (Human Protein Atlas): Plasma membrane
Gene Ontology:
Molecular function: protein binding; 2',3'-cyclic-nucleotide 3'-phosphodiesterase activity
Biological process: substantia nigra development; chemical synaptic transmission; cyclic nucleotide catabolic process
Cellular component: cytoplasm; extracellular exosome; extracellular region; melanosome; membrane; mitochondrion; plasma membrane; myelin sheath; synapse
Genetic constraint (gnomAD): Loss-of-function variants: 8 observed, 38.12 expected, observed/expected ratio (o/e) 0.21, 90% interval 0.12 to 0.38. The upper end of that interval is the gene's LOEUF score, 0.38, which puts it in group 1 of 6, group 1 being the genes least tolerant of losing a copy. Missense variants: 457 observed, 570.51 expected, observed/expected ratio (o/e) 0.8, 90% interval 0.74 to 0.87. Synonymous variants: 237 observed, 248.75 expected, observed/expected ratio (o/e) 0.95, 90% interval 0.86 to 1.06.
Homologues: Orthologues: chimpanzee CNP (100% identical), macaque CNP (98% identical), pig CNP (90% identical), rat Cnp (86% identical), mouse Cnp (85% identical), guinea pig CNP (84% identical), dog CNP (81% identical), tropical clawed frog cnp (52% identical), zebrafish cnp (30% identical), Caenorhabditis elegans nonu-1 (16% identical).
Diseases named in the same sentence as CNP in open-access papers:
CNP is named in the same sentence as 115 diseases in open-access papers, as found by Europe PMC text mining. Sharing a sentence is not in itself a finding about the gene and the disease. The quoted sentences say what the papers report.
schizophrenia (15 papers, 2009 to 2025). A major psychotic disorder characterized by abnormalities in the perception or expression of reality. "The CNP risk polymorphism was associated with lower gene expression which is consistent with CNP gene expression downregulation in schizophrenia." (PMID 24478629, 2014). "Genetic association analysis showed that OLIG2 is associated with schizophrenia and demonstrated an epistatic effect with 2′,3′-cyclic nucleotide 3′-phosphodiesterase (CNP) and ERBB4." (PMID 24478629, 2014). "Compatible with the underexpression of CNP mRNA in schizophrenia, the low-expressing A allele was significantly associated with schizophrenia in a case-control sample." (PMID 22937274, 2011). "Four independent studies meeting the selection criteria were included in the meta-analysis investigating association between CNP gene and schizophrenia." (PMID 19348671, 2009). "Five CNP single nucleotide polymorphisms (SNPs) were investigated in a Chinese Han schizophrenia case-control sample set (n = 180) using direct sequencing." (PMID 19348671, 2009). "CNP is thought to play a role in RNA metabolism and has also been linked to neuroinflammation in Alzheimer's disease, Down Syndrome, and schizophrenia." (PMID 30154697, 2018). "Similarly, a genetic association of the CNP gene was found for schizophrenia." (PMID 24478629, 2014). "For example, decreases in neocortical myelin development and myelin-related gene expression resulting in dysregulated CNP and myelin-associated protein (MAG) levels have been observed in patients with schizophrenia (SZ)." (PMID 34692694, 2021). "A robust reduction in CNP expression at both the mRNA and protein levels has been observed in the postmortem brains of patients with schizophrenia, bipolar disorder or MDD." (PMID 33144710, 2021). "Genetic and neuroimaging data have shown that the MAG, Olig2, and CNP genes can influence white matter integrity and cognitive performance in schizophrenia patients." (PMID 32425837, 2020). "Several of the upregulated genes (e.g. MAG, MAL and CNP) have previously been reported as downregulated in post-mortem brain samples from schizophrenia patients." (PMID 29187753, 2017). "In a recent human study, reduced CNP protein in the hippocampus and anterior cingulated cortex of patients with schizophrenia was also reported." (PMID 22937274, 2011). "Postmortem studies of anterior frontal cortex demonstrated less immunoreactivity of CNP in schizophrenia." (PMID 22937274, 2011). "The present study aims to investigate the relationship between CNP and schizophrenia in the Chinese population and the effect of different factors on the expression level of CNP in schizophrenia." (PMID 19348671, 2009). "2',3'-Cyclic nucleotide 3'-phosphodiesterase (CNP), one of the promising candidate genes for schizophrenia, plays a key part in the oligodendrocyte function and in myelination." (PMID 19348671, 2009). "Furthermore, OLIG2 expression significantly correlated in cerebral cortex with CNP and ERBB4, suggesting that variation in OLIG2 confers susceptibility to schizophrenia as part of a network of genes implicated in oligodendrocyte function." (PMID 24478629, 2014). "MAG, CNP, PLP1, and MBP were found reduced in mRNA samples from patients with schizophrenia in postmortem studies." (PMID 32425837, 2020). "In contrast, in situ hybridization of ACC white matter showed downregulation of mRNA for CNP and MAG in schizophrenia." (PMID 26909022, 2016). "In a targeted study, western blot for CNP showed decreased levels in the hippocampus but not the putamen from individuals with schizophrenia." (PMID 26909022, 2016). "Factors including gender, genotype, sub-diagnosis and antipsychotics-treatment were found not to contribute to the expression regulation of the CNP gene in schizophrenia." (PMID 19348671, 2009). "The results suggest that the CNP gene may not be involved in the etiology and pathology of schizophrenia in the Chinese population." (PMID 19348671, 2009).
depression (11 papers, 2013 to 2025). "An oligodendrocyte/myelin-associated genes, 2’,3’-cyclic nucleotide 3’-phosphodiesterase (CNP) was identified to be associated with catatonia-depression syndrom in the elderly." (PMID 25408907, 2013). "The antidepressant effects correlated with restored MBP, CNP, and IL-1β expression levels, suggesting that MBP/CNP deficiencies in depression may involve IL-1β elevation." (PMID 40500721, 2025). "The reversal of MBP/CNP deficits and IL-1β reduction suggests that myelin dysregulation in depression involves inflammatory-mediated oligodendrocyte impairment." (PMID 40500721, 2025). "Chronic unpredictable stress-induced depression was demonstrated to decrease the CNP+ cells in some regions of the hippocampus (e.g., CA1 or CA3 field, dentate gyrus) or in the medial prefrontal cortex of rats." (PMID 34299103, 2021). "Indeed, CNP gene expression in the CNS is altered in various stress-related regions of the brain following chronic treatment with corticosterone in an in vivo model of depression." (PMID 36267701, 2022). "Emerging evidence has shown that myelination-related transcriptional genes that are important for myelin structure (CNP, MAG, MOG) are significantly downregulated in patients with major depressive disorder (Aston, Jiang and Sokolov, 2005)." (PMID 35959443, 2022).
glioma (11 papers, 2008 to 2024). A benign or malignant brain and spinal cord tumor that arises from glial cells (astrocytes, oligodendrocytes, ependymal cells). "Meanwhile, the expressions of myelin-associated proteins (MBP, MOG, MAG and CNP) were unanimously reduced in gliomas." (PMID 30034322, 2018). "2010a) and enhancing the enzymatic activities of glutamine synthetase (GS) and 2′,3′-cyclic nucleotide 3′-phosphohydrolase (CNP) in rat C6 glioma cells." (PMID 27951737, 2017). "By contrast the peptide mass of 2',3'-cyclic-nucleotide 3'-phosphodiesterase (CNPase) at 1508.8739 Da represented by the grey lines is as expected not present in glioma vessels." (PMID 18312684, 2008).
Stroke (11 papers, 2010 to 2023). Sudden impairment of blood flow to a part of the brain due to occlusion or rupture of an artery to the brain. "In both proteomic analysis and Western blotting validation, TBN significantly upregulated the decreased CNP expression level in the stroke peri-infarct tissue." (PMID 27841332, 2016). "Unlike vimentin expresson, the expression level of CNP was dramatically decreased in the stroke peri-infarct tissue in comparison to that in the contralateral normal tissue." (PMID 27841332, 2016).
multiple sclerosis (8 papers, 2008 to 2025). A progressive autoimmune disorder affecting the central nervous system resulting in demyelination. "Consistent with existing data, IL-1β suppression, and related anti-inflammatory interventions restore CNP expression and myelin architecture in experimental multiple sclerosis models." (PMID 40500721, 2025).
ischemia (7 papers, 2018 to 2025). A hypoperfusion of the BLOOD through an organ or tissue caused by a PATHOLOGIC CONSTRICTION or obstruction of its BLOOD VESSELS, or an absence of BLOOD CIRCULATION. "Concerning glial elements, the ischemia-associated reduction of the SP-G signal co-occurred with an increased signal of oligodendroglial CNP and morphological changes of micro- and astroglia." (PMID 35682557, 2022). "Of note, CNP-derived degradation products of lower molecular weight were detectable in the ischemia-affected tissue." (PMID 37342767, 2023). "Therefore, CNP-related immunofluorescence intensity was measured in ischemia-affected areas, thereby confirming a 2.2-fold increase in the ischemic cortex and a 3.6-fold increase as compared to contralateral control areas." (PMID 37342767, 2023). "In this context, the glial proteins myelin basic protein (MBP) and the 2′,3′-cyclic-nucleotide 3′-phosphodiesterase (CNP) as well as the vasculature-associated basement membrane proteins laminin and collagen IV have been identified as ischemia-sensitive elements." (PMID 37342767, 2023). "However, while ischemia-affected areas are characterized by a reduction of MAP2-related fluorescence intensity, an opposite effect as indicated by an increased intensity is observed for CNP, MBP, collagen IV, and laminin." (PMID 37342767, 2023).
achondroplasia (5 papers, 2010 to 2018). Achondroplasia is the most common form of chondrodysplasia, characterized by rhizomelia, exaggerated lumbar lordosis, brachydactyly, and macrocephaly with frontal bossing and midface hypoplasia. "We have previously reported that overexpression of CNP in the cartilage or liver almost completely rescues skeletal growth failure in a mouse model for achondroplasia." (PMID 30235256, 2018). "We and the others have suggested the therapeutic potential of CNP or its analog for the treatment of skeletal dysplasia such as achondroplasia." (PMID 30235256, 2018). "Another valuable therapeutic candidate in the treatment of achondroplasia is CNP that works as an antagonist to FGFR3 signal." (PMID 25530967, 2014). "Exogenous administration of CNP-22, the 22-amino acid form of CNP, also stimulates skeletal growth in both normal mice and the achondroplasia mouse model, but requires a high-dose intravenous infusion (1.44 mg/kg/day) because of its short plasma half-life." (PMID 30235256, 2018). "Introduction of those constitutively active GC-B mutants may mimic the overexpressing CNP-induced GC-B activation in chondrocytes and is likely to suppress FGFR3-dependent achondroplasia." (PMID 23586811, 2013). "Thus, CNP acts on cartilage cells to antagonize FGFR3; indeed, in an example of "dueling pathways", an achondroplasia mouse model was rescued to normal growth by simultaneous overexpression of CNP." (PMID 20170480, 2010). "We previously reported that overexpression of CNP in chondrocytes counteracts dwarfism of an achondroplasia model mouse with activated FGFR-3 in the cartilage, and exhibited that inhibition of the MAPK/ERK pathway is one of the mechanism of an antagonistic effect of CNP to FGFR-3 signaling." (PMID 30235256, 2018). "Regardless, CNP is the most potent natriuretic peptide for reducing IOP in mammals, which suggests that the degradation resistant CNP analog developed for the treatment of achondroplasia may be an ideal peptide-based molecule to reduce IOP in the clinic." (PMID 24904270, 2014).
Alzheimer disease (5 papers, 2015 to 2026). A progressive, neurodegenerative disease characterized by loss of function and death of nerve cells in several areas of the brain leading to loss of cognitive function such as memory and language. "In T1DM, some of the terms annotated were related to myelin dysregulation (ARHGEF6, CNP, NADK2, PSAP, SLC25A12) and other neurological disorders, such as Alzheimer’s disease (i.e., POA2, APOC1, APOC3, CNP, GSK3B, PON1, PSAP, SELENBP1) or movement disorders." (PMID 39901093, 2025).
cardiac hypertrophy (5 papers, 2016 to 2025). "Additionally, mice with targeted deletion of the CNP gene in cardiomyocytes or fibroblasts exhibited increased cardiac hypertrophy and fibrosis in response to pressure overload in the left ventricle." (PMID 40563432, 2025). "In a mouse model of cardiac hypertrophy and remodelling induced by angiotensin II, CNP infusion also increased fractional shortening and decreased LVED dimension compared to the angiotensin II vehicle group, but no changes were observed with CNP when comparing with vehicle in the saline groups." (PMID 37493451, 2023).
glioblastoma (5 papers, 2015 to 2022). The most malignant astrocytic tumor (WHO grade IV). "Regarding CNP, the enzyme 2′,3′-cyclic nucleotide 3′ phosphodiesterase, it has until now only been linked to glioblastoma multiforme (GBM); CNP-positive patients had better survival rates than individuals with CNP-negative tumors." (PMID 36428851, 2022). "The expression of 2′,3′-cyclic nucleotide 3′ phosphodiesterase (CNP) correlates with glioblastoma patient survival." (PMID 35027588, 2022).
Anxiety (4 papers, 2017 to 2024). Intense feelings of nervousness, tension, or panic often arise in response to interpersonal stresses. "While no significant changes could be found in the open field test between CNP+/− and wild‐type mice, open arm visits in the elevated plus maze were significantly reduced in the CNP+/− group, meaning heterozygous mice showed normal motor activity and a mildly elevated anxiety profile." (PMID 35652161, 2022).
melanoma (4 papers, 2017 to 2021). A malignant, usually aggressive tumor composed of atypical, neoplastic melanocytes. "Multiple evidences suggested CNP had a pro-proliferation role in various cell lines, like melanoma cells, mouse Leydig cells, and osteoblastic cells." (PMID 33653372, 2021). "For GC-B, it was reported that activation of the CNP-GC-B-cGMP-PKGI pathway in melanoma cells promotes melanoma cell growth and migration in a MAPK-dependent manner." (PMID 32046325, 2020). "As CNP can be secreted from endothelial cells in response to inflammation, e.g., in the presence of cytokines, a new link between inflammation and melanoma has been proposed." (PMID 32046325, 2020). "We have shown earlier that CNP selectively kill A375 melanoma cells by increasing intracellular ROS levels, whose basic amount is significantly higher than in the normal (healthy) counterpart, the melanocytes." (PMID 31951630, 2020). "The increase of intracellular cGMP concentration in response to CNP was much stronger in metastatic melanoma cells than the respective response to ANP, suggesting a role of CNP in the cGMP signaling pathway in melanoma cells." (PMID 32046325, 2020). "The RAS/RAF/MEK/ERK pathway plays a key role in melanoma cell proliferation and survival It was previously observed that the high cGMP levels in response to CNP appeared to correlate with the aggressiveness/invasiveness of the tumor cells." (PMID 28515348, 2017). "We speculate that CNP induce higher hydrogen peroxide amounts via their SOD mimetic activity in melanoma cells compared to melanocytes due to an already higher basal ROS level in the tumor cells." (PMID 31951630, 2020). "In addition, simulated microgravity induced a more potent reduction of the expression of the CNP-sensitive GC-B than of the ANP-sensitive GC-A in highly metastatic melanoma cells." (PMID 32046325, 2020). "Concerning the role of pGC in melanoma, it has been shown that a large increase of CNP as a ligand of GC-B, which is released by the tumor vasculature particularly under inflammatory conditions, enhances the activity of PKGI in melanoma cells by increasing the intracellular cGMP concentration." (PMID 32046325, 2020). "In contrast to melanoma cells, CNP did not alter the dynamics of mitochondria in melanocytes." (PMID 31951630, 2020). "In addition to the CNP/H2O2 mediated mitochondrial dysfunction it cannot be excluded so far that other H2O2 dependent factors may also play a role in the CNP/H2O2 initiated selective increase in cytotoxicity and apoptotic cell death of melanoma cells." (PMID 31951630, 2020).
mental disorder (4 papers, 2015 to 2023). A disease that has its basis in the disruption of mental process. "In fact, some oligodendroglia specific risk factors (e.g., OLIG2, SOX10, and CNP), which are crucial for oligodendroglia development and myelination, are robustly dysregulated in major mental illnesses." (PMID 30524471, 2018). "Notably, this function requires a high-level expression of CNP in OLs, as evidenced by downregulated expression of CNP in mental disorders and animal models." (PMID 37642363, 2023).
atherosclerosis (3 papers, 2019 to 2025). A disease characterized by the build-up of fatty material and calcium deposition in the arterial wall resulting in partial or complete occlusion of the arterial lumen. "CNP is an autocrine and paracrine mediator released by endothelial cells, cardiomyocytes and fibroblasts, which can regulate important physiological functions of the cardiovascular system, as well as atherosclerosis." (PMID 34308964, 2021). "In the present study, we identified fluid shear stress and atherosclerosis as the main enriched pathways of differential hypomethylation related to up-regulation of GST and CNP genes in anti-atherogenesis." (PMID 34308964, 2021). "In the meantime, sexual reproduction, cohesin complex and protein C-terminus binding was functionally linked to differential hypomethylation, while fluid shear stress and atherosclerosis were identified as the main pathways related to up-regulated GST and CNP." (PMID 34308964, 2021).
COVID-19 (3 papers, 2021 to 2024). A disease caused by infection with severe acute respiratory syndrome coronavirus 2. "This work highlights the importance of cytosolic ROS for SARS-CoV-2 virion assembly and identifies CNP as a potential therapeutic target for COVID-19." (PMID 38117830, 2023). "Collectively, this work shows the potential of mPTP inhibition and reduction in ROS production as a treatment for COVID-19 and the potential of CNP to be a new SARS-CoV-2 antiviral target." (PMID 38117830, 2023). "Eight ISGs were downregulated in Asymptomatic as compared with severe COVID-19 cases; CNP, CSF1, IRF1, IFITM10, IRF2BP2, IRF2BPL, SLC25A28 and SOCS3." (PMID 34824360, 2021).